EGFR (epidermal growth factor receptor)
Diseases named in the same sentence as EGFR in open-access papers (continued):
Sharing a sentence is not in itself a finding about the gene and the disease.
lung adenocarcinoma (continued). "However, CAR-T cells against LSCC have never been reported although CAR T cells that target FAP, EphA2 and EGFR have been developed for the treatment of lung adenocarcinoma." (PMID 26684028, 2016). "However, the emergence of “targeted” drug therapy with TKIs in EGFR‐mutant lung adenocarcinoma has substantially mitigated this concern." (PMID 26747090, 2016). "Our study showed that TLGWBR (TLGWBR ≥259.85), EGFR mutation status, and serum LDH level for baseline 18F-FDG PET/CT were significant independent prognostic factors for PFS and OS in 176 patients with advanced lung adenocarcinoma." (PMID 27336755, 2016). "We performed further detailed analyses on samples from three specific studies on patients with glioblastoma multiforme (n=136), lung adenocarcinoma (n=230) and head and neck squamous cell carcinoma (n=279), where EGFR protein levels were compared with c-CBL transcript levels." (PMID 27612423, 2016). "Since various studies have now indicated an important role for the IL-6/STAT3 axis as a mediator of resistance to EGFR inhibition in lung adenocarcinomas, we have also analyzed whether IL-6 was upregulated in the cell models utilized here." (PMID 27248176, 2016). "In conclusion, we note that more comprehensive genomic characterization of the tumor reveals alterations that may confer resistance to EGFR TKI in EGFR-mutant lung adenocarcinoma patients." (PMID 27121209, 2016). "In conclusion, early radiologic parameters of tumors including size and volume change after TKI treatment can be used to predict treatment response and OS in EGFR mutant lung adenocarcinoma patients, with the stronger prognostic value of the change in volume compared with that of size." (PMID 26984681, 2016). "Today, in routine practice upfront reflex EGFR mutation testing should be performed in all patients with adenocarcinoma of the lung and in squamous cell lung cancer with a non-smoking history." (PMID 27032107, 2016). "In conclusion, for patients with advanced lung adenocarcinoma, the use of first-line EGFR-TKIs in patients who harbored the EGFR 19 del might be associated with higher ORR and longer PFS compared with patients who carried the L858R mutation." (PMID 27001083, 2016). "This study shows that the EGFR mutation is common in females, non-smokers and those patients with lung adenocarcinoma." (PMID 27992557, 2016). "In these models, lung adenocarcinoma is generated by doxycycline-induced lung epithelial expression of transgenic EGFRL858R, a TKI-sensitive mutation, and by EGFRL858R/T790M, which accounts for approximately 60% of acquired resistance to EGFR TKIs." (PMID 27494838, 2016). "In that study, only one of 31 ILD patients with lung adenocarcinoma had an EGFR mutation; this patient had a non-UIP radiographic pattern." (PMID 27350261, 2016). "The PIK3CA mutation rate in lung adenocarcinoma with acquired resistance to EGFR TKI is not higher than that in EGFR TKI-naïve tissue specimens (2.9% (6/207) vs. 1.8%; p = 0.344)." (PMID 27734950, 2016). "Screening lung adenocarcinoma patients with clinical cancer gene test may aid in selecting out those who show primary resistance to EGFR TKI (NCT01697163)." (PMID 27121209, 2016). "Moreover, we observed a secondary T790M EGFR mutation in lung adenocarcinoma (LUAD) and resistance to EGFR-targeted therapies (Gefitinib and Afatinib), as well as resistance of NRAS mutated melanoma patients to a BRAF inhibitor." (PMID 27397505, 2016). "In addition, 16 out of 28 patients (57.1%) with WT K-ras had a mutant EGFR in the primary lung adenocarcinoma." (PMID 27070580, 2016). "In our previous study of the mutation status of five genes in lung adenocarcinoma, EGFR mutations were more common in female patients and non-smokers." (PMID 27191886, 2016).
lung adenocarcinoma (continued). "The identification of therapeutically tractable molecular targets, particularly epidermal growth factor receptor (EGFR) mutation and anaplastic lymphoma kinase (ALK) rearrangement, has led to the dramatic improvement in personalized therapy for lung adenocarcinoma." (PMID 27145277, 2016). "Recently, rs2736100-C was further identified to be more intimately associated with female, non-smoking, EGFR-mutation-positive lung adenocarcinoma." (PMID 26934125, 2016). "With the discovery of epidermal growth factor receptor (EGFR) mutations, anaplastic lymphoma kinase (ALK) rearrangements, and effective targeted therapies, therapeutic options are expanding for patients with lung adenocarcinoma." (PMID 27200298, 2016). "Altogether, EGFR mutation in the MPE of lung adenocarcinoma is generally between 60% and 70% in Taiwan, regardless of the patient’s sex, smoking status, and age." (PMID 27352172, 2016). "Findings of this study demonstrate potential molecular guidance of patient management of lung adenocarcinoma with or without EGFR-activating mutations." (PMID 26824984, 2016). "Use of epidermal growth factor receptor tyrosine kinase inhibitors (EGFR TKI) produces dramatic response and favorable prognosis in patients with lung adenocarcinoma harboring epidermal growth factor receptor (EGFR) mutations, especially exon 19 deletion and exon 21 L858R point mutations." (PMID 26862733, 2016). "The biological characteristics of patients with the epidermal growth factor receptor (EGFR) mutation differ greatly from those with wild-type EGFR; this leads to the use of different therapies and different clinical outcomes in patients with advanced (≥stage IIIB) lung adenocarcinoma." (PMID 27336755, 2016). "Recurrent mutations in CDH10 have recently been reported in EGFR/KRAS/ALK mutation-negative lung adenocarcinoma in never-smokers and as a prognostic mutation signature in colorectal cancer." (PMID 27093186, 2016). "Patients with lung adenocarcinoma who have never smoking frequently contain mutation within tyrosine kinase domain of the epidermal growth factor receptor(EGFR) gene." (PMID 26985396, 2016). "In this study, we hypothesized that osimertinib could inhibit glycolysis in EGFR-mutant lung adenocarcinoma lines." (PMID 27861144, 2016). "Finally, lung adenocarcinoma patients with acquired resistance to EGFR-TKIs were given an exploratory treatment of PD 0332991." (PMID 27825114, 2016). "Whether EGFR tyrosine kinase inhibitors or ALK inhibitors are still effective for these special lung adenocarcinomas with clear cell component like lung adenocarcinoma is uncertain and calls for further investigation." (PMID 27013585, 2016). "Epidermal growth factor receptor (EGFR) mutations, including a known exon 19 deletion (19 del) and exon 21 L858R point mutation (L858R mutation), are strong predictors of the response to EGFR tyrosine kinase inhibitor (EGFR-TKI) treatment in lung adenocarcinoma." (PMID 27001083, 2016). "To understand the impact of PIK3CA mutation on clinical characteristics of advanced lung adenocarcinoma and the treatment response of EGFR TKIs, we examined PIK3CA and EGFR mutations from lung adenocarcinoma patients, and analyzed their clinical treatment outcomes." (PMID 27734950, 2016). "As there was a significantly higher proportion of never-smokers in the younger patient, why did younger lung adenocarcinoma patients have a lower EGFR mutation rate than that of older patients?" (PMID 27191886, 2016). "Using next-generation sequencing, we screened 739 mutation hotspots in 46 cancer-related genes in EGFR L858R-mutant lung adenocarcinomas from 29 patients who received EGFR-TKI therapy; 13 had short (< 3 months) and 16 had long (> 1 year) progression-free survival (PFS)." (PMID 25823662, 2015).
lung adenocarcinoma (continued). "Furthermore, ROR1, a constituent gene of Wnt signaling pathway, plays a sustainer role in EGFR-mediated prosurvival signaling in lung adenocarcinoma via signaling cross-talk and was therefore reported to be a potential therapeutic target." (PMID 25599599, 2015). "Using Shp2 siRNAs, Dox-inducible shRNAs, Shp2 binding defective Gab1 mutant, and PTP-inactive Shp2 mutant, we have provided evidence that inhibition of Gab1-Shp2 interaction and Shp2 PTP activity suppress Erk1/2 activation in the HCC827 lung adenocarcinoma cells that harbor a mutant EGFR." (PMID 25730908, 2015). "Moreover, clinical studies that combine RET inhibitors and EGFR TKIs with other targeted drugs are warranted for the lung adenocarcinoma patients harboring concurrent KIF5B-RET fusion gene and EGFR or KRAS mutations." (PMID 26268359, 2015). "In contrast to previous reports, our results indicate that the KIF5B-RET fusion gene may coincide with EGFR or KRAS mutations, albeit at a lower frequency, in lung adenocarcinomas." (PMID 26268359, 2015). "It was identified that EGFR was often overexpressed and aberrantly activated in NSCLC, and several activating mutations within the kinase domain of the EGFR gene were detected in lung adenocarcinomas." (PMID 25683726, 2015). "In this prospective cohort of treatment-naïve advanced lung adenocarcinoma, the T790M mutation was found in only 0.4% of our Chinese patients using the ARMS assay, accounting for 0.8% of EGFR M+ patients, all of which were observed concomitantly with the EGFR L858R mutation." (PMID 26599344, 2015). "To further confirm that Shp2, Gab1-Shp2 interaction, and Shp2 PTP activity mediate Erk1/2 activation in lung adenocarcinoma cells that harbor mutant EGFR, we compared the pErk1/2 level in isogenic HCC827 cells containing two different Dox-inducible Shp2 shRNAs." (PMID 25730908, 2015). "Taken together, our data suggest one-step screening platform for KIF5B-RET as well as EGFR, K-RAS, ALK oncogenic mutations be necessary for lung adenocarcinoma patients because EGFR or KRAS mutation are not infrequently found in KIF5B-RET-positive patients." (PMID 26268359, 2015). "As IPASS data revealed NSCLC patients with mutant EGFR had a high response rate to 1st-line TKI treatment, 30% patients with lung adenocarcinoma and EGFR mutation had no response to 1st-line EGFR-TKI treatment." (PMID 26609535, 2015). "Current clinical approaches to overcome resistance in lung adenocarcinoma are the use of irreversible and mutant-selective EGFR inhibitors, and combining an EGFR inhibitor with a drug targeting a resistance pathway, such as the combination of erlotinib and an MET inhibitor." (PMID 26462152, 2015). "However, miR-7 overexpression was also shown to attenuate EGFR expression in lung adenocarcinoma CLI-5 cells, suggesting the existence of an EGFR/miR-7 regulatory loop." (PMID 26308064, 2015). "Primary resistance to EGFR-TKIs was identified in the human lung adenocarcinoma cell line A549." (PMID 25925741, 2015). "Interestingly, our study demonstrated that EGFR and EML4-ALK mutations were observed in 50% (11/22) of the lung adenocarcinoma patients." (PMID 26332764, 2015). "The BRAF gene copy number was analyzed using quantitative polymerase chain reaction amplifications in 29 surgically treated lung adenocarcinoma cases without EGFR or Kras mutations from Nagoya City University Hospital (Nagoya, Japan)." (PMID 25621040, 2015). "Finally, BIM and mTOR expression were determined in our panel of EGFR-mutant lung adenocarcinoma cell lines and correlated with the half maximal inhibitory concentration (IC50) of gefitinib." (PMID 26639561, 2015). "The detection of MLH1 V384D in blood or non-tumor tissue samples of patients with EGFR L858R-mutant lung adenocarcinoma also suggests that it is not a somatic mutation but a germline mutation/polymorphism." (PMID 25823662, 2015).
lung adenocarcinoma (continued). "In our study, systematic testing of 762 lung adenocarcinoma for EGFR mutations revealed a prevalence of 61%—regardless of smoking status." (PMID 25955322, 2015). "Interestingly, most of these strongly staining RTKs were mutually exclusive, evoking the oncogenic driver mutations (EGFR, KRAS, ALK, and ROS1) observed in lung adenocarcinoma." (PMID 25989941, 2015). "Its effect on wild-type or mutant EGFR lung adenocarcinoma cells was further evaluated." (PMID 25980579, 2015). "The authors also reported histology transformation in tumors with acquired resistance; five patients with lung adenocarcinoma before EGFR-TKI treatment were found to have small-cell lung cancer (SCLC) in drug-resistant tumor biopsies, while retaining the original EGFR mutation." (PMID 26310719, 2015). "A significant fraction of patients with lung adenocarcinomas harboring activating epidermal growth factor receptor (EGFR) mutations do not experience clinical benefits from EGFR tyrosine kinase inhibitor (TKI) therapy." (PMID 25823662, 2015). "The primary lung adenocarcinoma, however, harbored a wild-type EGFR sequence." (PMID 25663915, 2015). "However, clinical analysis in a Japanese study showed that strong ERβ expression predicts a better clinical outcome than weak expression in patients with lung adenocarcinoma following EGFR-TKIs therapy." (PMID 26096604, 2015). "In addition, with the establishment of first-line treatment using EGFR-TKI, the knowledge of EGFR mutation status in treatment-naïve advanced NSCLC, especially lung adenocarcinoma, is of great importance for clinical decision." (PMID 26599344, 2015). "In conclusion, MLH1 V384D polymorphism is associated with primary resistance to EGFR-TKIs in patients with EGFR L858R-positive lung adenocarcinoma and may potentially be a novel biomarker to guide treatment decisions." (PMID 25823662, 2015). "Expression of these GOF EGFR mutants in type II lung pneumocytes directed by a rat Clara cell secretory protein (CCSP) promoter in CCSP-rtTA/tetO-EGFR mutant bitransgenic mice induces lung adenocarcinoma." (PMID 25730908, 2015). "The study contains data on H3255, a lung adenocarcinoma cell line sensitive to EGFR-directed tyrosine kinase inhibitors, and H1975, another lung adenocarcinoma cell line resistant to first-generation reversible EGFR-TKIs, such as Erlotinib." (PMID 26678097, 2015). "GOF EGFR mutants induce lung tumors in transgenic mouse models of lung adenocarcinoma." (PMID 25730908, 2015). "Cancer molecular heterogeneity might explain the variable response of EGFR mutant lung adenocarcinomas to tyrosine kinase inhibitors (TKIs)." (PMID 25904052, 2015). "Therefore, screening for the EGFR and KRAS mutations, and ALK and KIF5B-RET translocations should be considered during initial diagnosis of lung adenocarcinomas." (PMID 26268359, 2015). "Human lung adenocarcinomas (LUAD) contain mutations in EGFR in ∼15% of cases and in KRAS in ∼30%, yet no individual adenocarcinoma appears to carry activating mutations in both genes, a finding we have confirmed by re-analysis of data from over 600 LUAD." (PMID 26047463, 2015). "In the present study, increased BRAF gene copy number was identified in 10.3% of Japanese lung adenocarcinoma patients without EGFR or Kras mutations." (PMID 25621040, 2015). "In our analysis, we observed an improvement in the survival of patients with lung adenocarcinoma over the years, which may be attributed to the introduction of EGFR inhibitors." (PMID 26091466, 2015). "To confirm and further explore this conclusion, we directly induced the expression of mutant KRAS or mutant EGFR in established lines of human lung adenocarcinoma cells known to be driven by either mutant EGFR (PC9 cells; in-frame deletion in exon 19) or by mutant KRAS (H358 cells; G12C)." (PMID 26047463, 2015).
lung adenocarcinoma (continued). "In a recent study of lung adenocarcinomas, mutation rates for EGFR (39%), KRAS (4%), ALK (15%), and HER2 (5%) in never-smoker groups differed from rates in current or former smoker groups (10%, 35%, 4%, and 1%, respectively)." (PMID 25760072, 2015). "EGFR mutations were the most frequently found mutation in lung adenocarcinomas of female never-smokers (124 cases, 63%)." (PMID 25760072, 2015). "Because EGFR gene mutation status in Uighur patients with lung adenocarcinoma is not known, we designed this study to provide genetic evidence for effective treatment with EGFR-TKI therapy." (PMID 25886900, 2015). "In this study, we generated transgenic mice expressing a PTP-defective (catalytic residues C459S/D425A mutations), dominant-negative Shp2 mutant (tetO-Shp2CSDA) to assess the effects of Shp2 PTP inhibition in a transgenic mouse model of mutant EGFR-driven lung adenocarcinoma." (PMID 25730908, 2015). "Although EGF stimulates Shp2 activation, it is not entirely clear whether Shp2 is active in lung epithelial cells harboring GOF EGFR mutants and whether Shp2 is important for mutant EGFR to drive lung adenocarcinoma." (PMID 25730908, 2015). "The IGF-1R (insulin-like growth factor 1 receptor) protein level, which has been associated with resistance to EGFR-TKIs, was also analyzed to explore the potential mechanisms behind the effects of the GAS5/gefitinib combination on gefitinib-resistant lung adenocarcinoma cells." (PMID 25925741, 2015). "Because EML4-ALK fusion is not as frequent as EGFR gene mutation, it would be important to efficiently and accurately identify those lung adenocarcinomas that harbor ALK rearrangements in clinical practice to guide the appropriate therapy 9,10." (PMID 24403104, 2014). "The impact of detection methods on the rates of response to EGFR-tyrosine kinase inhibitors (TKIs) in EGFR-wild type (wt) lung adenocarcinoma patients is unknown." (PMID 25215536, 2014). "Our findings suggest that hinokitiol could be a promising compound for treating EGFR-TKI-resistant lung adenocarcinomas." (PMID 25105411, 2014). "Substitution of EGFR G719, the first residue of this motif, to serine, cysteine, or alanine, has been observed in lung adenocarcinomas (~1%), and one G719S mutant and four G724S mutants have been reported in colorectal carcinomas that were sequenced for EGFR (COSMIC database)." (PMID 24894453, 2014). "Efficacy of erlotinib in 261 lung adenocarcinoma patients without detectable EGFR mutations at initial molecular testing." (PMID 25215536, 2014). "Many researchers have found that EGFR mutations mainly occur in exons 19 and 21 and the mutant population is mainly lung adenocarcinoma patients, especially Asian women that are never smokers." (PMID 24743427, 2014). "With the discovery of epidermal growth factor receptor (EGFR) mutations, anaplastic lymphoma kinase (ALK) rearrangements, and effective targeted therapy, personalized medicine has become a reality for patients with lung adenocarcinoma." (PMID 25505733, 2014). "Herein, we hypothesized that inhibition of EGFR in lung adenocarcinomas might be achieved via RBM5 overexpression." (PMID 25441176, 2014). "In our previous study, we reported that 90% of 52 lung adenocarcinoma samples from East Asian never smokers harbored driver mutations in just EGFR, KRAS, HER2 and ALK genes." (PMID 24533074, 2014). "Although genome-scale characterization of lung adenocarcinoma has been performed, a comprehensive somatic mutation analysis of EGFR/KRAS/ALK-negative lung adenocarcinoma in never-smokers has not been conducted." (PMID 24576404, 2014). "EGFR is a cell-surface receptor for ligands in the epidermal growth factor family and is present in a wide range of diseases such as glioblastoma multiforme, lung adenocarcinoma and colorectal cancer." (PMID 24669769, 2014).